TIAM1 (TIAM Rac1 associated GEF 1)
Diseases named in the same sentence as TIAM1 in open-access papers (continued):
Sharing a sentence is not in itself a finding about the gene and the disease.
tumor (continued). "In addition, Tiam1 transgenic mice developed larger and more aggressive neoplasm than wild-type mice." (PMID 24069171, 2013). "Comparison of tumor volume in Tiam1 transgenic mice and wild-type mice." (PMID 24069171, 2013). "Tiam1 is a potential modifier of tumor initiation and progression." (PMID 24069171, 2013). "Studies using mouse models suggest that Tiam1 may function as both an oncogene and tumor suppressor during tumor progression." (PMID 20819206, 2010). "In tumor types in which elevated expression is observed, Tiam1 may support cancer progression by regulating motility and metastasis." (PMID 20819206, 2010). "A similar dual contribution by Tiam1 to tumor progression has been proposed for APC-induced tumors." (PMID 20819206, 2010). "Because we observed a positive correlation between motility and Tiam1 expression in our panel of tumor cell lines, we determined whether Tiam1 supports the motile phenotype." (PMID 20819206, 2010). "The contribution of Tiam1-mediated activation of Rac1 to the upregulation of such tumour-promoting genes may represent one mechanism by which the Tiam1/Rac1 signalling module contributes to tumour development in the colon." (PMID 18826597, 2008). "The guanine nucleotide exchange factor, Tiam1, specifically activates the Rho-like GTPase Rac and Tiam1-Rac signaling affects cell migration, invasion, and metastasis of tumour cells." (PMID 17003780, 2006). "Thus, we hypothesized that circTIAM1 might be partly involved in tumor progression as a circRNA originating from TIAM1." (PMID 35022405, 2022). "Interestingly, Tiam1 depletion, although largely suppressing tumour formation, promotes malignant progression, indicating a dual oncogene/tumour suppressor role for Tiam1." (PMID 33758078, 2021). "In CRC tissues and SW480 cells, the expression of circRNA-ACAP2 and Tiam1 is increased, while the expression of miR-21-5p is decreased, indicating that circRNA-ACAP2 and Tiam1 may promote the growth of tumor cells, while miR-21-5p acts as an inhibitor of tumor growth." (PMID 33627631, 2021). "Thus, this association could display TIAM1 and SFRP2 as two candidates to be potential tumor suppressor genes." (PMID 32517740, 2020). "However, the underlying mechanisms through which Par3 silencing triggers Tiam1 activation and rapid tumor metastasis are not fully understood." (PMID 27588399, 2016). "Tiam1 may also represent a new molecular target for tumor therapy." (PMID 26369827, 2015). "Tiam1 is a general guanine nucleotide exchange factor that regulates Rho proteins with multiple effects; thus, alterations in its expression might contribute to tumor occurrence, progression, and migration." (PMID 26369827, 2015). "Thus, modulators of Tiam1 gene expression, such as miRNAs, may be predicted to have a profound effect on tumor progress." (PMID 24551096, 2014). "However, when average tumor volumes were analyzed on 29 tumors selected randomly from each of the two groups, a significantly increased tumor size was observed in Tiam1 transgenic mice with a mean tumor volume (23.260±2.119 mm3) 4.7-fold higher (P<0.001) than in wild-type mice (4.929±0.580 mm3)." (PMID 24069171, 2013). "Thus, during early stages of tumor progression, suppression of Tiam1 expression may be necessary to disrupt cell-to-cell adhesions and support epithelial-mesenchymal transition." (PMID 20819206, 2010). "However, as a limited population of tumor cells acquire an invasive phenotype, Tiam1 expression may be restored to support invasion or polarized motility." (PMID 20819206, 2010). "As our results suggest, Tiam1-mediated Rac1 activation may feed back to augment nuclear Wnt signalling, leading to sustained Tiam1/Rac1 signalling and as a consequence, the enhanced transcription of target genes that may be important for tumour initiation and/or progression." (PMID 18826597, 2008).
tumor (continued). "Therefore, it is conceivable that increased Tiam1 expression might induce transcription of distinct oncogenes and/or inhibit transcription of distinct tumour suppressor genes, which consequently contributes to oncogenic transformation." (PMID 17003780, 2006). "Through the regulation of YAP1, TEAD4 binds to the TIAM1 enhancer region, thereby activates the expression of TIAM1 and subsequently increases the activity of RAC1 and induces the formation of invadopodia formation and promotes tumor metastasis." (PMID 40746611, 2025). "Upon further literature review, we found that TIAM1 and RAP1GAP have already been reported as an oncogene and a tumor suppressor gene, respectively, in TC, with their roles validated through cellular biology experiments 35-37." (PMID 40092686, 2025). "Among these genes, six genes are potential regulator of tumor metastasis, including CEMIP, FBN2, TIAM1, ITGA2, ARHGAP42, and GPRIN3." (PMID 38971758, 2024). "Significant changes have been detected in the tumor microenvironment pathway including genes MMP19, MMP24, and CSF2, as well as PLAU, BCL2, TIAM1 and Rac1." (PMID 38003292, 2023). "For ITGA2, SLC1A5, TIAM1, TNIK, and ABTB2, several studies showed that their high expression played a significant role in promoting tumor cell growth and inhibiting cell apoptosis from chemotherapy in different kinds of cancers." (PMID 35267472, 2022). "However, a loss of Tiam1 is not always associated with tumor progression." (PMID 35875120, 2022). "Both TIAM1 and SFRP2 hypermethylation leads to decrease expression of both genes and further increase cell proliferation and tumor growth." (PMID 32517740, 2020). "The relative expression of Tiam1 mRNA in the EL4 cell spheroids generated in AmCA hydrogels and fresh EL4 tumor were 5.9-fold and 5.6-fold greater than the 2D-cultured EL4 cells, respectively." (PMID 29416753, 2018). "MiR-10b is a potent pro-metastatic metastamiR and previous studies have shown that miR-10b targets several tumor suppressors such as, HOXD10, KLF4, TIAM1 and others." (PMID 25426550, 2014). "Recently, more reports have shown that miR-29 family regulated tumorigenesis and tumor progression by targeting DNMT3A, DNMT3B, TIAM1, cyclin E, MMP2, ID1, SPARC and COL3A1." (PMID 23936390, 2013). "This suggests that TIAM1 may function as an oncogene, while RAP1GAP, JUN, and GPX3 might act as tumor suppressors." (PMID 40092686, 2025). "Using this signature, together with TIAM1 and RAC1 expression, we performed hierarchical cluster analysis on RNA-sequencing (RNA-seq) data from 81 primary SCLC tumors, 44 circulating-tumor-cell-derived explant (CDX) models, and 49 SCLC cell lines." (PMID 34758330, 2021). "Although significantly fewer in number, tumours lacking Tiam1 are more likely to become malignant, indicating that Tiam1 deficiency promotes malignant conversion." (PMID 33758078, 2021). "The tumor-suppressive miR-29c is also a metastasis suppressor that inhibits NPC cell migration, invasion, and metastasis by targeting the T cell lymphoma invasion and metastasis 1 gene, TIAM1, directly." (PMID 31456943, 2019). "Moreover, consistent with the Tiam1 expression, Rac1 and c-Myc expression was much higher in the 3D-cultured EL4 cells (2.1-fold and 2.3-fold, respectively) and fresh EL4 tumor (2.2-fold and 2.4-fold, respectively) than the 2D-cultured EL4 cells." (PMID 29416753, 2018). "Indeed TIAM1 is located on HSA21 and has been shown to be a critical regulator of different aspects of Ras-induced tumour formation." (PMID 28266534, 2017). "Through histological analysis, we found that although the tumor incidence and the tumor number per animal were not affected by Tiam1, the average tumor volumes were significantly increased in Tiam1-transgenic group than that in wild-type mice." (PMID 24069171, 2013).
tumor (continued). "Levels of Vav 1 and TIAM-1 were also higher in tumours but were not significantly different (0.66 ± 0.35 v 0.07 ± 0.027; p = 0.095 for Vav1 and 1196 ± 743 v 261 ± 107; p = 0.22 for TIAM-1)." (PMID 18925966, 2008). "It is possible that depending on the context, like other molecules (e.g., Tiam1 TGF-β), PERK signaling may have different functions during tumor progression." (PMID 17637831, 2007). "Despite these functions the potential prognostic relevance of Tiam1 expression in human tumours has not been investigated yet." (PMID 17003780, 2006). "However, no impairment in the growth of tumor cells was observed in the control group (only TIAM1- KO) in the mouse model." (PMID 37993945, 2023). "Tiam1 protein expression was significantly associated with TNM stage (P < 0.0005) and lymph node status (P < 0.0005), but not with patients’ age, gender, differentiation and tumor size." (PMID 24661909, 2014). "Given these heterogeneous effects of Tiam1 on migration and invasion of epithelial cells in vitro, the effect of increased Tiam1 expression in a given tumour in vivo on DFS might be positive or negative." (PMID 17003780, 2006). "It has also been shown that some BCAFs lacking Tiam1 protein expression produce high levels of osteopontin (OPN), which in turn promotes epithelial-mesenchymal transition, tumor stem cell phenotype." (PMID 39418248, 2024).
cancer (78 papers, 2006 to 2026). A tumor composed of atypical neoplastic, often pleomorphic cells that invade other tissues. "The most common GEFs implicated in cancer are T-cell lymphoma invasion and metastasis 1 (Tiam1), Trio, Vav1/2/3, Ect2, Phosphatidylinositol 3,4,5-trisphosphate (PIP3)-dependent Rac exchanger 1 (P-Rex1), and Dock1." (PMID 32322580, 2020). "Herein, we identified T-lymphoma invasion and metastasis-inducing protein-1 (TIAM1) as one of the Wnt-signaling associated genes which drives self-renewal and its expression is upregulated by cancer associated fibroblasts (CAFs)." (PMID 30890693, 2019). "Altering Tiam1 expression in CAFs induces changes in invasion, migration, epithelial-mesenchymal transition, and cancer stem cell characteristics in associated breast cancer cells." (PMID 28769537, 2017). "In a pilot study we found Tiam1 protein expression to be readily detectable in cancer-associated fibroblasts in 15 of 17 cases of DCIS (ductal carcinoma in situ), but decreased in cancer-associated fibroblasts in 19 cases of invasive cancers (p < 0.001)." (PMID 26821678, 2016). "We show that although Rac1 deletion throughout the intestinal epithelium causes defects in intestinal homeostasis, loss of VAV2, VAV3 and TIAM1 is sufficient to strongly suppress cancer phenotypes and tumourigenesis induced by APC loss, whilst leaving the normal intestinal epithelium unperturbed." (PMID 33397922, 2021). "Notably, 2 tumors showed a TIAM1 variant allele ratio close to 100% (variants A163V and D424E), suggesting that they are homozygous in the cancer cells." (PMID 28423360, 2017). "Since one of the main molecular signatures that were enriched in the TIAM1-depleted cells was associated with EMT, we speculate that TIAM1 may be associated with suppressing cancer stem cell identity, since cancer stem cells are characterized by a mesenchymal cell gene expression program." (PMID 28416184, 2017). "TIAM1 promotes cancer cell proliferation, invasion, and metastasis via multiple pathways, including AKT/mTOR signaling and ERK/STAT3 signaling." (PMID 40228435, 2025). "This translates to complicated roles of Tiam1 in cancer, which can be pro- or anti-oncogenic depending on cancer type and stage." (PMID 38077328, 2023). "Here, we identified that in contrast to other cancers of epithelial origin, TIAM1 is required for the migration and invasion of NSCLC cells." (PMID 37748077, 2023). "Tiam1 is frequently overexpressed in various types of cancer including breast, prostate, colorectal and cervical cancers." (PMID 38017477, 2023). "miR-21 downregulation increases Tiam1 expression which is attributed to cancer metastatic potential." (PMID 37583428, 2023). "Further, it leads to an increase in the activation of Rac1 through Tiam1 expression that induces cancer cell migration toward metastasis." (PMID 35875090, 2022). "Tiam1 expression is increased in cancer and contributes to the spread of cancer cells to new areas of the body, a process known as metastasis." (PMID 34415021, 2021). "This has resulted in a wealth of observations related to the contribution of RAC-GEFs such as ASEF1, ASEF2 or TIAM1, both to early adenoma formation, and to pathways critical for control of aggressive cancer cell phenotypes." (PMID 33397922, 2021). "For example, CtBP2 associates with KLF8 (Kruppel-like factor 8) to activate the expression of Tiam1 (T-cell lymphoma invasion and metastasis 1), thereby promoting cancer cell migration." (PMID 32140068, 2020). "For example, CtBP2 associates with KLF8 to directly activate the expression level of TIAM1 (T-lymphoma invasion and metastasis-inducing protein 1) to promote human cancer cell migration." (PMID 31929749, 2020). "It should also be noted that some studies have identified an oncogenic role for miRNAs targeting TIAM1, thus more work is needed to uncover the context-dependent effects of TIAM1 on cancer progression." (PMID 32353968, 2020).
cancer (continued). "SETDB1 knockdown in HCC cell lines exhibited downregulation of T-lymphoma invasion and metastasis gene (Tiam1), reducing cancer migration and suggesting the positive correlation between SETDB1 and Tiam1 in HCC." (PMID 33255318, 2020). "Collectively, these results indicate that inhibition of TIAM1 suppresses cancer stemness in part through inhibition of Rac1 phosphorylation." (PMID 30890693, 2019). "One of the potential mechanisms of TIAM1-induced enhancement of cancer stemness is through Rac activation." (PMID 30890693, 2019). "Based on our experimental data, we showed that CM collected from CAFs with reduced expression of TIAM1 resulted in enhanced chemosensitivity, suggesting existence of a mechanism by which CAFs exert oncogenic effects in cancer cells through TIAM1." (PMID 30890693, 2019). "Confirming our in vitro data, the expression of Nanog, Oct4, and ALDH were all downregulated in TIAM1 suppressed tumors, suggesting that these TIAM1 suppressed tumors contained a lower population of cancer stem cells." (PMID 30890693, 2019). "TIAM1 knockdown resulted in significant reduction of spheroid formation in numbers indicating that TIAM1 is involved in regulation of cancer stemness (p < 0.001)." (PMID 30890693, 2019). "Loss of Pard3 has been shown to promote tumorigenesis in different human cancers via Tiam1/Rac1-dependent mechanisms." (PMID 30171257, 2019). "NSC23766 inhibits interactions between of Rac and GEFs, including Trio and Tiam1, inhibiting Rac activation and cancer cell invasion, metastasis, and neoangiogenesis in multiple cancer subtypes." (PMID 28423521, 2017). "Accumulating evidence has shown that Tiam1 is expressed at relatively high levels in a variety of human malignancies, and a correlation between Tiam1 overexpression and several human cancers has been identified." (PMID 27562113, 2016). "In 19 areas of DCIS, cancer-associated fibroblasts showed decreased expression of OPN and increased cytoplasmic expression of Tiam1." (PMID 26821678, 2016). "Accordingly, Tiam1 has been shown to act as a metastasis-related gene in a variety of cancers, including breast cancer, colorectal cancer (CRC), prostate cancer, lung cancer, Ras-induced skin tumors and renal cell carcinoma." (PMID 24551096, 2014). "Recent studies have identified that Tiam1 is a functional target of miR-10b, miR-21 and miR-31 in different cancers, revealing the miRNA regulatory networks on Tiam1 expression." (PMID 24551096, 2014). "Conversely, the immunoreactive patterns of Tiam1 were predominantly positively identified in the cancer tissues." (PMID 24661909, 2014). "T lymphoma invasion and metastasis protein (Tiam1) is up-regulated in variety of cancers and its expression level is related to metastatic potential of the type of cancer." (PMID 23950931, 2013). "By targeting distinct molecules such as matrix metalloproteinase regulators TIMP3 and TIAM1, miR-21 plays an essential role in cancer progression and metastasis." (PMID 24039846, 2013). "This suggests that the role of nuclear TIAM1 in migration is dependent on the cellular context and may differ by cancer type." (PMID 37748077, 2023). "Studies of Tiam1 function have largely focused on epithelial cells, neurons, and cancer cells." (PMID 38077328, 2023). "Tiam1 has been identified a specific activator of Rho-like GTPases Rac1, and the activation Tiam1-Rac signaling plays a crucial role in enhancing invasion and metastasis of various cancers." (PMID 37986114, 2023). "Therefore, it is important to understand the role of TIAM1 and its interactors in different cancer contexts to exploit its therapeutic potential." (PMID 37748077, 2023). "One option would be to inhibit specific cancer-associated RAC1-GEFS, an approach exemplified by inhibitors such as NSC23766, a small-molecule inhibitor which blocks the interaction of a subset of GEFs, including TIAM1, with RAC1." (PMID 33397922, 2021).